IL6 (interleukin 6)
Diseases named in the same sentence as IL6 in open-access papers (continued):
Sharing a sentence is not in itself a finding about the gene and the disease.
cancer (continued). "The demonstration that IL-34 stimulates IL-6 induction in both TICs and LPMCs supports further the protumorigenic role of IL-34, as IL-6 can target directly cancer cells and activate signaling pathways that promote CRC cell growth and survival." (PMID 33298879, 2020). "IL-6 plays a role in immunosuppression by driving differentiation of myeloid suppressor cells together with TGF-β in cancer pathogenesis." (PMID 32772917, 2020). "Although there have been many studies on the relationship between serum IL-6 and clinical outcomes in various cancers, there have been few studies investigating the relationship between IL-6 and IL-6R in tissues and clinical outcomes." (PMID 32138303, 2020). "In patients with cancer, IL-6 binds to its receptor IL-6R and exerts its effect by activating the signal transducer and activator of transcription 3 (STAT3)." (PMID 32230855, 2020). "We previously reported that activated HSCs promoted cancer cell progression through paracrine or autocrine interleukin-6 (IL-6)." (PMID 32895059, 2020). "IL-6 is a robust biomarker in OSCC and statins are well known to suppress IL-6 expression in normal and cancer cells." (PMID 32731382, 2020). "Third, inflammatory markers such as IL6, IL8, CRP, and TNFα are associated with fatigue in cancer survivors." (PMID 33317113, 2020). "Monocytes migrate into peritoneal lesions using the C-C chemokine ligand 2 (CCL2) derived from CAFs and differentiate into the M2 phenotype by macrophage colony-stimulating factor (M-CSF) and IL-6 secreted from CAFs and cancer cells." (PMID 33081727, 2020). "The experimental blockade of IL-6 with the simultaneous inhibition of IL-8 significantly attenuated the invasiveness of cancer cells in vitro." (PMID 33114676, 2020). "IL-6 promotes cancer stemness and oncogenicity of osteosarcoma cells by upregulating a secreted phosphorylated glycoprotein osteopontin." (PMID 32855767, 2020). "IL6 was overproduced in cells after treatment with LY2835219, and it was reported to be closely associated with cancer stemness." (PMID 33116117, 2020). "One explanation is that high interleukin-6 levels produced by cancer cells inhibit the synthesis of albumin." (PMID 33028394, 2020). "As a principal downstream signaling molecule, IL‐6 is also involved in cancer initiation, promotion, progression, and metastasis." (PMID 32638533, 2020). "Different studies in animal models and cancer patients demonstrated that high levels of interleukin 6 (IL-6) correlate with muscle wasting, inhibition of protein synthesis, promotion of protein degradation and autophagy in myotubes." (PMID 32373612, 2020). "Here, we present data demonstrating that autocrine activin A signalling in cancer cells is needed for their release and systemic distribution of IL‐6." (PMID 31436048, 2020). "We also demonstrated that, unlike in untreated endothelial cells, the stimulation of these cells with the CV extract increased the production of IL-6, IL-8, and MMP-9, whereas cancer cells only released slightly more IL-6." (PMID 33260615, 2020). "Several works recently showed the increased expression of IL-6 and/or its receptors in bone metabolism, hematopoiesis, pathogenesis, inflammatory responses, and cancer progression." (PMID 33266223, 2020). "We employed CR1 to block exogenous activation of C3 and detected a weakened expression of p-STAT3 and IL-6 compared with AG490-treated cancer cells." (PMID 31928530, 2020). "NF-κB (especially RELA) can upregulate a spectrum of targets involved in chronic inflammation and cancer initiation such as cyclooxygenase 2, IL-6, IL-23, and IL-1β." (PMID 32972405, 2020). "Enhanced STAT-3activity in cancer can be due to excess of growth factors and IL6-familycytokines in the cancer microenvironment." (PMID 32167126, 2020).
cancer (continued). "In prostate cancer, TLR2 is expressed on cancer cells and mediates the pro-tumorigenic effects induced by some pathogens such as Trichomonas vaginalis and Mycoplasma through the induction of IL-6 and IL-8 production and consequent stimulation of EMT." (PMID 33321934, 2020). "Interleukin (IL)-6, tumor necrosis factor (TNF)-α, and transforming growth factor (TGF)-β are also closely associated with several cancer-related symptoms and adverse events of anti-cancer therapy, such as cachexia and fatigue." (PMID 33050250, 2020). "Previous studies have reported that activation of STAT3 or the IL-6-JAK-STAT3 signaling cascade in cancer cells promotes oncogenesis 52-55." (PMID 31938049, 2020). "White adipose tissue (WAT) is a significant source of inflammatory cytokines accounting for more than 30% of circulating interleukin (IL)-6 and this and other inflammatory cytokines have been linked to WAT atrophy in cancer." (PMID 32934774, 2020). "IL-6 and IL-10 create a favorable environment to support tumorigenesis by increasing the cancer cell proliferation, angiogenesis, metastasis and contribute to enhancing the immune suppression." (PMID 32508531, 2020). "The C-reactive protein enhances secretion of interleukin 6 (IL-6) and, synergized with IL-6, protects cancer cells from chemotherapy-induced apoptosis." (PMID 32533048, 2020). "The final molecule predicted is IL-6, which belongs to the chemotactic cytokine family and correlates with occurrence, invasion, and metastasis of cancer." (PMID 32832554, 2020). "We found that the co-expressed genes of MIR22HG are significantly enriched in number of cancer-related signaling pathways, including IL6-JAK-STAT3, TNFA signaling and TGFβ signaling pathway." (PMID 32127004, 2020). "Cancer cell-derived IL-6 and IL-8 upregulated endothelin receptor expression on cancer cells and the production of endothelin from astrocytes." (PMID 33322216, 2020). "Previous studies on IL-6 reveal to be a multifaceted player in cancer; it can recruit neutrophils and T cells, but it can also activate several cancer cell growth-inducing signaling pathways." (PMID 32225009, 2020). "Various studies have indicated that STAT-3 is a molecular target for curcumin via IL-6 modulation for various cancer types." (PMID 32806551, 2020). "IL-6, as a cytokine, is capable to act on cancer cells to activate JAK-STAT pathway, thus inducing carcinogenic effects such as proliferation, apoptosis inhibition, metastasis, and angiogenesis." (PMID 31949128, 2020). "Genes and proteins involved in the regulation of cancer cell proliferation and metastasis, such as IL6, IL8, and VEGFA, were similarly regulated under RPM and spaceflight conditions." (PMID 32070055, 2020). "Along with its essential role in the progression of cancer, the IL-6/JAK/STAT3 signaling axis incorporates various unexpected components and miRNAs that contribute to JAK/STAT3 activation in cancer." (PMID 31952344, 2020). "Regardless, in vitro, we show that there is a direct effect of activin A signalling on IL‐6 gene transcription and IL‐6 protein secretion from the cancer cells." (PMID 31436048, 2020). "IL-6 is produced by a variety of cells, including inflammatory cells, fibroblasts, endothelial cells, and cancer cells." (PMID 32637576, 2020). "The activation of STAT3, JAK/STAT, mTOR, sonic hedgehog and nuclear factor κ B (NFκB) signalling is important for the IL-6 effect on cancer cells and supports the metastatic spreading of malignant disease." (PMID 33114676, 2020). "Previously, an indirect pro-angiogenic effect of IL-6 has been reported from endothelial co-cultures with other cell types such as synovial, peritoneal, and different types of cancer cells." (PMID 32517159, 2020). "Although the autocrine IL‐6 regulation of cancer progression is well documented, the paracrine effects of IL‐6 secreted from stromal cells or immune cells on cancer development have also been reported." (PMID 32491253, 2020).
cancer (continued). "At the same time, cancer can increase the expression of proinflammatory IL-6 and tumour necrosis factor-α and consequently decrease serum albumin, resulting in a vicious cycle." (PMID 33299415, 2020). "A pleiotropic protein that is a pro-inflammatory cytokine called IL-6 was involved in biological activities, involving cancer and autoimmune diseases in addition to other processes." (PMID 32961987, 2020). "One of the widely used chemotherapeutic drugs in treatment of advanced cancers is cisplatin, which triggers inflammatory cytokine IL-6 and IL-8 production." (PMID 32434541, 2020). "Both RAGE and IL-6 play vital roles in linking cancer with inflammation through multiple signaling pathways." (PMID 33187505, 2020). "The JAK/STAT3 signaling pathway activated by the IL6/IL-6R/IL-6Rβ (gp130) complex plays a key role in the growth and development of many human cancers." (PMID 33363013, 2020). "A high amount of fibroblasts was also associated with a higher infiltration of anti-cancer immune cells, such as CD8+ T-cells and dendritic cells, together with higher inflammatory signaling, including IL2/STAT5 and IL6/JAK/STAT3 signaling." (PMID 32485981, 2020). "Constitutive activation of STAT3 leading to cancer is the result of increased cytokine production (IL-6, IL-10), continuous cytokine receptor activation (VEGFR/EGFR), or non-receptor tyrosine kinases (JAKs, Src, Abl)." (PMID 33158194, 2020). "Our results clearly demonstrate that autocrine activin A signalling in the cancer cell culture promotes the release of IL‐6." (PMID 31436048, 2020). "Our previous study showed that Trichomicin, a natural compound derived from Trichoderma hazianum, exerted potent anti-inflammatory and anticancer activity in vitro, and induced apoptosis in cancer cells through inhibition of IL-6/Stat3 signaling." (PMID 32317968, 2020). "Bone-metastasized cells from primary cancers such as lung and breast cancers release cytokines, such as IL-6, IL-8, M-CSF, and monocyte chemotactic protein-1, which affect osteocyte functions." (PMID 32708317, 2020). "Cancer-related proinflammatory cytokines, such as interleukin-6 (IL-6) and interleukin-1 (IL-1), as well as tumor necrosis factor-α (TNF-α) inhibit albumin production, leading to cancer cachexia." (PMID 33176752, 2020). "The cytokines and their receptors utilized through TAMs during cancer progression include IL-6, IL-12, IL-10, IL-23, TNF, and TLRs." (PMID 32283687, 2020). "CAIX is thought to be involved in promoting survival and enhancing the invasive behavior of cancer cells via the IL-6/Notch-3/CAIX axis." (PMID 32707920, 2020). "Because autocrine activin A signalling clearly stimulates IL‐6 secretion from the cancer cells, we asked if this involved increased transcription of the IL‐6 gene." (PMID 31436048, 2020). "IL-6 is studied in oncology and cardioncology because it is a key promoter of cancer survival, chemoresistance, anticancer-induced cardiotoxicity, and cancer progression." (PMID 33182653, 2020). "IL-6 is a pleiotropic cytokine released in large amounts during infection, autoimmunity, and cancer." (PMID 33158194, 2020). "The interaction between liver and cancer cells is thought to be mediated by mononuclear cells through IL-6 activation." (PMID 32230855, 2020). "MSLN plays a pivotal role in cancer cell survival/proliferation by NF-kB activation which induces IL-6 expression." (PMID 33344222, 2020). "Neutrophils play crucial roles in the pathogenesis of cancer by enhancing the proliferation, invasion, and metastasis of cancer cells via the release of cytokines and chemokines such as interleukin (IL)-6 and tumor necrosis factor-α (TNF-α)." (PMID 32676164, 2020). "Prostate cancer cells and α-SMA+ CAFs cooperatively recruited macrophages and polarized them to M2-like TAMs via CCL2, CXCL12, and IL-6, while recruited macrophages conferred malignant and activation phenotypes on cancer cells and CAFs, respectively." (PMID 33050237, 2020).
cancer (continued). "Their moderate positive correlation with inflammation markers (CRP, IL-8, IL-6) sustains their role in cancer progression." (PMID 33375435, 2020). "Interleukin 6 (IL-6) is recognized as a potent inflammatory cytokine that is widely expressed in a variety of immune cells and malignant tumors." (PMID 33322216, 2020). "HNRNPs participated in cancer‐related pathways including protein secretion, mitotic spindle, G2/M checkpoint, DNA repair, IL6/JAK/STAT3 signal and coagulation, of which hnRNP genes of HNRNPF, HNRNPH2, HNRNPU and HNRNPUL1 are more likely to be implicated." (PMID 32915499, 2020). "Targeting IL-6 in cancer patients has been demonstrated to impact cancer-related symptoms and to have minor role in cancer invasion." (PMID 32468851, 2020). "Lignan can inhibit binding affinity between NF-κB and AP-1 transcription factors to interleukins (IL-6 promoter and IL-6) production through p38/NF-κB and AP-1 signaling pathways in cancer." (PMID 32046692, 2020). "Interleukin (IL)-6, which is increased by viral infection and inflammation in cancer, exhibited a pleiotropic activity." (PMID 33086629, 2020). "Reciprocally, educated SCs secret IL6 to activate STAT3 signaling in cancer cells, thus augmenting cancer cell invasion and metastasis in vitro and in vivo." (PMID 32308766, 2020). "As IL-6 impact on cancer cells increased serine-threonine kinase Pim1, over stimulation also led to AR transcriptional reactivity." (PMID 32961987, 2020). "In a number of studies, IL-6 acts as a protector of cancer cells from therapy-induced DNA damage, oxidative stress, and apoptosis, contributing to repair." (PMID 32963755, 2020). "Pre-clinical reports from our group at Johns Hopkins Medicine and others also showed that deregulation of IL-6 can occur during some severe pathological instances like autoimmune disorders, cardiovascular disorders, and different types of cancer." (PMID 33352869, 2020). "Our in vitro data show that activin A acts in an autocrine or paracrine manner to promote secretion of IL‐6 from the cancer cells." (PMID 31436048, 2020). "This indicated that stromal IL6 increased glycolysis in cancer cells and suppressed the entry of glucose to oxidative phosphorylation." (PMID 33177492, 2020). "Studies have demonstrated that telomerase can directly regulate recruitment to promoters of NF-κB target genes, such as those encoding interleukin-6 (IL-6) and tumor necrosis factor alpha (TNF‐α) that are critical for inflammation and cancer progression." (PMID 33329574, 2020). "The role of IL-6 in cooperation with IL-8 in neovascularisation and thus in the progression of cancer was also confirmed." (PMID 33114676, 2020). "A recent meta‐analysis showed a reliable association between inflammatory markers (including CRP, IL‐1, and IL‐6) and self‐reported depressive symptoms, although studies on cancer patients remained extremely limited (Howren, Lamkin, & Suls, 2009)." (PMID 32790154, 2020). "Members of the let-7 family can target inflammatory cytokines, such as IL-6 by let-7a and IL-13 by let-7f, shown to contribute to cancer-cell apoptosis and anti-inflammatory action respectively." (PMID 32716937, 2020). "Mechanistically, cancer cells secret interleukin 1β (IL1β) to activate the nuclear factor kappa B (NF-κB)/p65 pathway in SCs, thereby increasing the production of interleukin 6 (IL6) from SCs." (PMID 32308766, 2020). "IL-6 has been reported to be produced by several cancer types, including PCa, endowed with pleiotropic effects." (PMID 33569050, 2020). "RKIP inhibits the metastatic potential of cancer through the reduction of IL-6, Raf, or c-Src-mediated STAT3 activation by direct interaction with STAT3." (PMID 31952344, 2020).
cancer (continued). "Their expansion and migration can be induced by molecules produced during chronic inflammation and cancer, such as GM-CSF, IL-6, IL-10, IFN-γ, and VEGF." (PMID 33171792, 2020). "In fact, we have recently shown that cancer cells activate breast stromal fibroblasts in an IL-6-dependent manner." (PMID 32414408, 2020). "ApcMin/+ mice with cancer cachexia showed significant muscle wasting in presence of a 10-fold increase of serum IL-6 levels compared to control groups." (PMID 33329046, 2020). "IL-6-mediated activation of JAK/STAT3 signaling has been shown to increase the proliferation of cancer cells 28,29." (PMID 33123268, 2020). "Studies have shown that the STAT3 pathway is involved in IL-6 regulation of several cancer cell functions, such as proliferation and metastasis." (PMID 32201532, 2020). "The main factors affecting the biological activity of cancer cells are IL-10, IL-6, TGF-β, VEGF, CCL18, CCL22, and microRNA." (PMID 32456078, 2020). "Cancer-related inflammation is one of the hallmarks of cancer, and interleukin-1 (IL-1), IL-6, tumor necrosis factor alpha (TNF-α), and C-reactive protein (CRP) are widely recognized as biomarkers of systemic inflammation related to breast cancer." (PMID 33108715, 2020). "In summary, these data show that PIK3CA activation overrides regulation of stemness traits by IL-6 trans-signaling and renders cancer cells more independent from microenvironment control." (PMID 33020483, 2020). "Most of the genes in the subnetworks were inflammatory cytokines and participated in TNF signaling pathways and pathways in cancer, such as Ccl2, Ccl20, Csf1, Cx3cl1, Cxcl1, Cxcl3, Il6, Birc3, Map3k8, Nos2, Nfkb2, Tnfrsf1b, and Vcam1." (PMID 33042984, 2020). "With the aid of starBase that the mRNA of IL-6, a characteristic inflammatory cytokine closely involved in cancers, was an appropriate target for them." (PMID 31949128, 2020). "Currently, the use IL-6 in improving the quality of life and in decreasing severe cancer symptoms like fatigue and cachexia in patients with GIT cancer are subjects for further research." (PMID 32961987, 2020). "TNF-α and IL-6 are two indicators of cancer cachexia, and the levels of these two cytokines are usually tested in many studies to determine the therapeutic effect." (PMID 32020864, 2020). "Inhibition of the IL-6/STAT3 pathway is a promising approach for cancer treatment; however, STAT3 inhibitors that can be used at present in clinical cancer therapy are limited in their efficiency, specificity, and safety." (PMID 31511651, 2020). "After 100 days of exposure, there appeared to be a significantly higher overexpression of cancer-related cytokines Tnf and Il6, anti-apoptotic Bcl2, NF-κB factor Rela, and oncogenic factor Egfr compared to the 45-day exposure." (PMID 32344873, 2020). "Nintedanib greatly reduced the levels of cancer-promoting cytokines, such as interleukin (IL)-6 (IL-6) and IL-8, secreted by CAFs." (PMID 32015511, 2020). "Excess IL-6 production drives carcinogenesis and for some types of cancers high circulating levels of IL-6 indicate a poor prognosis." (PMID 32486470, 2020). "In this study, through the comparison of IL-6 protein expression between activated fibroblasts and ESCC cells, we found that IL-6 concentrations in activated fibroblasts were 80-fold greater than those in cancer cells." (PMID 32637576, 2020). "On the other hand, TAMs are involved in cancer progression through the release of specific protumoral cytokines such as interleukin IL-6, IL-8 and IL-10." (PMID 33375467, 2020). "Significantly reduced IL‐6 secretion (P < 0.05) from the cancer cells is consistently observed when using biological, chemical, and genetic approaches to interfere with the autocrine activin A loop." (PMID 31436048, 2020). "These markers are known to be stimulated by cancer-related inflammatory factors, such as interleukin-6 thus sensitively reflecting cancer-related inflammation." (PMID 32451768, 2020).